LUZP1 (leucine zipper protein 1)
Description:
F-actin cross-linking protein. Stabilizes actin and acts as a negative regulator of primary cilium formation. Positively regulates the phosphorylation of both myosin II and protein phosphatase 1 regulatory subunit PPP1R12A/MYPT1 and promotes the assembly of myosin II stacks within actin stress fibers. Inhibits the phosphorylation of myosin light chain MYL9 by DAPK3 and suppresses the constriction velocity of the contractile ring during cytokinesis. Binds to microtubules and promotes epithelial cell apical constriction by up-regulating levels of diphosphorylated myosin light chain (MLC) through microtubule-dependent inhibition of MLC dephosphorylation by myosin phosphatase (By similarity). Involved in regulation of cell migration, nuclear size and centriole number, probably through regulation of the actin cytoskeleton (By similarity). Component of the CERF-1 and CERF-5 chromatin remodeling complexes in embryonic stem cells where it acts to stabilize the complexes (By similarity). Plays a role in embryonic brain and cardiovascular development (By similarity).
Synonyms: LUZP
Tractability: PROTAC: ubiquitination databases record sites on it; its protein half-life has been measured.
Gene: Protein-coding gene on chromosome 1 (23,084,030 to 23,178,152, reverse strand). Ensembl gene ENSG00000169641.
Subcellular location: Cytoplasm, cytoskeleton, microtubule organizing center, centrosome; Cytoplasm, cytoskeleton, cilium basal body; Midbody; Chromosome, centromere; Cytoplasm, cytoskeleton, spindle; Cytoplasm, cytoskeleton, stress fiber; Nucleus; Cell projection, dendrite; Perikaryon; Cell junction, tight junction
Subcellular location (Human Protein Atlas): Actin filaments; Centrosome; Cytokinetic bridge; Cytosol; Plasma membrane; Vesicles
Gene Ontology:
Molecular function: actin filament binding; protein binding; microtubule binding
Biological process: contractile ring contraction; negative regulation of cilium assembly; stress fiber assembly; apical constriction; protein localization to actin cytoskeleton; regulation of protein complex stability
Cellular component: actin cytoskeleton; actin filament; centrosome; chromosome, centromeric region; ciliary basal body; extracellular exosome; membrane; midbody; spindle midzone; stress fiber; CERF complex; nucleus; perikaryon; tight junction; bicellular tight junction; dendrite; spindle
Genetic constraint (gnomAD): Loss-of-function variants: 25 observed, 76.93 expected, observed/expected ratio (o/e) 0.32, 90% interval 0.24 to 0.45. The upper end of that interval is the gene's LOEUF score, 0.45, which puts it in group 2 of 6, group 1 being the genes least tolerant of losing a copy. Missense variants: 1,142 observed, 1,366.5 expected, observed/expected ratio (o/e) 0.84, 90% interval 0.8 to 0.88. Synonymous variants: 481 observed, 534.68 expected, observed/expected ratio (o/e) 0.9, 90% interval 0.83 to 0.97.
Homologues: Orthologues: chimpanzee LUZP1 (99% identical), macaque LUZP1 (96% identical), pig LUZP1 (88% identical), dog LUZP1 (87% identical), guinea pig LUZP1 (83% identical), rat Luzp1 (82% identical), mouse Luzp1 (80% identical), rabbit LUZP1 (74% identical), tropical clawed frog luzp1 (36% identical), zebrafish luzp1 (34% identical), Caenorhabditis elegans C49H3.6 (5% identical). Paralogues in human: FILIP1 (25% identical), FILIP1L (20% identical), CTTNBP2NL (8% identical).
Diseases named in the same sentence as LUZP1 in open-access papers:
LUZP1 is named in the same sentence as 18 diseases in open-access papers, as found by Europe PMC text mining. Sharing a sentence is not in itself a finding about the gene and the disease. The quoted sentences say what the papers report.
colorectal cancer (2 papers, 2021 to 2026). A primary or metastatic malignant neoplasm that affects the colon or rectum. "Our results coincide with the reported anti-proliferative effect of Luzp1 downregulation in colorectal cancer cells and the reported increase in proliferation due to Luzp1 upregulation in uterine fibroids." (PMID 33869174, 2021). "Furthermore, Poel and colleagues claimed that LUZP1 downregulation might mediate chemotherapy sensitivity mechanisms in colorectal cancer cells, potentially through cell cycle arrest." (PMID 33869174, 2021).
glioma (2 papers, 2021 to 2024). A benign or malignant brain and spinal cord tumor that arises from glial cells (astrocytes, oligodendrocytes, ependymal cells). "In this study, we detected and correlated the expression of hsa_circ_0001367, miR-545-3p and LUZP1 in glioma tissues and cell lines." (PMID 34869035, 2021). "Circ_0001367 was reduced in glioma, and its upregulation could enhance LUZP1 expression to inhibit glioma progression by sponging miR-545-3p." (PMID 39192374, 2024). "By searching the online database GEPIA, we found that LUZP1 was downregulated in glioma tissues." (PMID 34869035, 2021). "Leucine zipper protein (LUZP1), predominantly expressed in brain, is reportedly involved in many diseases; however, its role in glioma remains unknown." (PMID 34869035, 2021). "Taken together, the results of this study demonstrate that the circ_0001367/miR-545-3p/LUZP1 axis may be a novel target for glioma therapy." (PMID 34869035, 2021). "Herein, we showed that LUZP1 was significantly downregulated in glioma tissues and cells." (PMID 34869035, 2021). "The MTT and EdU assays suggested that LUZP1 deletion could block the suppressive effect of miR-545-3p inhibitor on glioma proliferation." (PMID 34869035, 2021). "Finally, an in vivo experiment was conducted, which demonstrated that circ_0001367 inhibited glioma growth in vivo by modulating miR-545-3p and LUZP1." (PMID 34869035, 2021). "In addition, it demonstrated that circ_0001367 suppresses the proliferation, migration and invasion of glioma cells by sponging miR-545-3p to regulate LUZP1." (PMID 34869035, 2021). "Furthermore, function assays indicated that LUZP1 functions as a suppressor in glioma and is regulated by miR-545-3p." (PMID 34869035, 2021). "The results demonstrated that LUZP1 was downregulated in glioma tissues compared with ANTs." (PMID 34869035, 2021). "In addition, function assays indicated that LUZP1 deletion could block the suppressive effect of circ_0001367 overexpression on glioma proliferation, migration and invasion." (PMID 34869035, 2021). "The circ_0001367/miR-545-3p/LUZP1 axis may be a novel target for glioma therapy." (PMID 34869035, 2021).
breast carcinoma (1 paper, 2021). "In line with the genomic analysis and the gene dosage-mRNA expression association, using Cancertool we found the mRNA levels of LUZP1 to be significantly reduced in prostate cancer, and non-significantly in breast cancer." (PMID 33869174, 2021).
cholangiocarcinoma (1 paper, 2021). A carcinoma that arises from the intrahepatic biliary tree (intrahepatic cholangiocarcinoma) or from the junction, or adjacent to the junction, of the right and left hepatic ducts (hilar cholangiocarcinoma). "Interestingly, we found genomic aberrations in LUZP1 at high frequency in cancer specimens, reaching an alteration frequency of almost 80% in cholangiocarcinoma and greater than 40% in 13 out of the 54 cancer types that we analyzed." (PMID 33869174, 2021).
colon carcinoma (1 paper, 2022). "Expression of LUZP1 was specifically downregulated for liver metastasis of colon carcinoma." (PMID 35795065, 2022).
glioblastoma (1 paper, 2019). The most malignant astrocytic tumor (WHO grade IV). "As MCAF1 for glioblastoma, LUZP1 may have a similar role in CRC and inhibition may reduce β-catenin signaling." (PMID 31546954, 2019).
liver cancer (1 paper, 2019). An epithelial or non-epithelial malignant neoplasm that arises from the liver. "Upregulation of LUZP1 is associated with a poor prognosis of liver cancer." (PMID 32010623, 2019).
neural tube defect (1 paper, 2021). A congenital defect characterized by failure of the neural tube to close completely; this results in the presence of openings in the brain or spinal cord. "Mutations in mouse Luzp1 resulted in cardiovascular defects and cranial Neural Tube Defects (NTD) accompanied by elevated apoptosis of mesenchymal cells, demonstrating its crucial role in embryonic heart and brain development." (PMID 33869174, 2021).
osteosarcoma (1 paper, 2023). A usually aggressive malignant bone-forming mesenchymal neoplasm, predominantly affecting adolescents and young adults. "In osteosarcoma, the YY1 transcription factor induces upregulation of circFIRRE and partially increases mRNA and protein levels of LUZP1 by adsorbing miR-486-3p and miR-1225-5p, promoting tumor cell growth and angiogenesis, thereby driving primary osteosarcoma progression and lung metastasis." (PMID 37819576, 2023).
Townes-Brocks syndrome (1 paper, 2020). Townes-Brocks syndrome (TBS) is a rare genetic disorder characterized by the triad of imperforate anus, dysplastic ears often associated with sensorineural and/or conductive hearing impairment, and thumb malformations. "Through our studies on Townes-Brocks Syndrome (TBS), a rare disease linked to abnormal cilia formation in human fibroblasts, we uncovered the leucine-zipper protein LUZP1 as an interactor of truncated SALL1, a dominantly-acting protein causing the disease." (PMID 32553112, 2020).
ventricular septal defect (1 paper, 2020). The presence of a defect (opening) in the septum that separates the two ventricles of the heart. "TBS cardiac defects include atrial or ventricular septal defect, the latter of which is seen in Luzp1 knockout mice." (PMID 32553112, 2020).
cancer (5 papers, 2020 to 2024). A tumor composed of atypical neoplastic, often pleomorphic cells that invade other tissues. "Despite this evidence, focused research on LUZP1 is necessary to elucidate the role that it might have in cellular features underlying cancer development." (PMID 33869174, 2021). "In this work, we demonstrate that heterozygous loss of LUZP1 is frequent in different cancer types." (PMID 33869174, 2021). "Another perspective would be that complete LUZP1 loss might be counterselected in cancer due to the antiproliferative and proapoptotic effects, and this explains the frequency of heterozygous losses." (PMID 33869174, 2021). "Here we show that LUZP1 exhibits frequent genomic aberrations in cancer, with a predominance of gene deletions." (PMID 33869174, 2021). "We first aimed to characterize the genomic alterations of LUZP1 reported in various cancer types using a publicly available webtool (cBioPortal)." (PMID 33869174, 2021). "In summary, our study demonstrates that LUZP1 controls proliferative and invasive features in cancer, thus providing a feasible explanation for its frequent copy number aberrations in various cancer types." (PMID 33869174, 2021). "From our analysis, LUZP1 emerges as a potential cancer-relevant gene, exhibiting genomic and transcriptional perturbation pattern suggestive of a tumor suppressive function." (PMID 33869174, 2021). "As observed in Luzp1–/– cells, a switch from proliferation to migration/invasion is a common event in the context of cancer." (PMID 33869174, 2021). "As the cytoskeleton and cilia are implicated in metastasis and tumor suppression, we examined roles for LUZP1 in the context of cancer." (PMID 33869174, 2021). "Our results point to an unprecedented role for LUZP1 in the regulation of cancer features through the control of actin cytoskeleton." (PMID 33869174, 2021). "It was reported that LUZP1 could regulate cancer features by modulating actin cytoskeleton stability and ciliogenesis." (PMID 35986280, 2022). "We next evaluated whether copy number aberrations would influence LUZP1 gene expression across several cancer types based on the TGCA Pancancer Atlas database (cBioPortal)." (PMID 33869174, 2021). "However, the Circ_0001367/miR-545-3p/LUZP1 axis suppressed cancer progression in GBM/LGG." (PMID 39027151, 2024). "In fact, we cannot rule out the possibility that LUZP1 and EPLIN (and/or other LUZP1 interactors) might have a cooperative role in the context of cancer." (PMID 33869174, 2021).
tumor (4 papers, 2021 to 2023). "The heterozygous loss of LUZP1 observed in tumor samples could be the consequence of the balance between the advantage of decreasing LUZP1 levels enough to promote invasion and the counterselection of complete loss to avoid genomic instability or cell division defects leading to apoptosis." (PMID 33869174, 2021). "In the second place, we attempted to verify the role of LUZP1 in tumor progression and angiogenesis." (PMID 35986280, 2022). "Results showed that reduction of LUZP1 expression led to weakened proliferation, migration and invasion abilities in OS cells and weakened tube formation capabilities in HUVEC, indicated that LUZP1 was the target of circFIRRE that affected tumor growth, lung metastasis and angiogenesis." (PMID 35986280, 2022). "LUZP1 shows homology to FILIP1 (Filamin A Interacting Protein 1), a protein interactor of filamin and actin, and FILIP1L (FILIP1 Like), a suppressor of tumor cell migration." (PMID 33869174, 2021).
LUZP1 also shares sentences with these, for which no sentence is quoted: cardiomyopathy (1 paper); depression (1); fibroids (1); left ventricular noncompaction (1); prostate carcinoma (1).